BRAF (B-Raf proto-oncogene, serine/threonine kinase)
Diseases named in the same sentence as BRAF in open-access papers (continued):
Sharing a sentence is not in itself a finding about the gene and the disease.
thyroid cancer (continued). "Aim of the present study was to test the effect of PLX4720 on the secretion of CXCL8 in normal human thyroid (NHT) cells, in the BCPAP, 8305C and 8505C thyroid cancer cell line harboring the BRAF V600e mutation and in the TPC-1 thyroid cancer cell line bearing the RET/PTC re-arrangement." (PMID 30867499, 2019). "The prognostic value of BRAF p.V600E mutated thyroid cancer is still the subject of controversy." (PMID 31835496, 2019). "Activation of BRAF has originated as the most prevalent oncogenic mutation in thyroid carcinoma." (PMID 30760304, 2019). "Specimens of pituitary adenomas and thyroid cancer were collected for BRAF mutation assessments." (PMID 29593792, 2018). "Future studies should explore whether HCP5 can affect BRAF mutations, which occur concomitantly in thyroid cancer." (PMID 29515098, 2018). "The BRAF V600E mutation was detected in the PTCs of the two patients with thyroid cancer." (PMID 29593792, 2018). "Though the limited number of thyroid neoplasms in this study prevents us from drawing conclusions regarding the correlation between the BRAF mutation and thyroid cancer in acromegaly, it is likely that the BRAF V600E mutation occurs often in the PTCs of acromegalic patients." (PMID 29593792, 2018). "Therefore, we conclude that the pharmacological inhibition of MAPK signaling in undifferentiated thyroid cancer cells carrying a BRAF or Ras mutation induces p38 phosphorylation, which subsequently activates CREB and leads to L-GILZ transcriptional activation." (PMID 29467389, 2018). "In addition, human thyroid cancers that are BRAF mutated or have other mutations have different miRNA expression profiles." (PMID 29713312, 2018). "Moreover, thyroid cancer with BRAF V600E and TERT promoter mutations has been associated with worse clinico-pathological outcomes." (PMID 29720964, 2018). "Although there are few studies in the literature, higher PKM2 expression in thyroid carcinomas appears to be significantly associated with the BRAF mutation, suggesting that this enzyme may be a potential therapeutic target in this type of cancer." (PMID 29629339, 2018). "In addition, 25–50% of thyroid cancers are BRAF mutated and constitutive activation of BRAF signaling leads to aggressive malignancies, lacking typical traits of thyroid differentiation and, thus, poorly responsive to radioiodine therapy." (PMID 29033690, 2017). "Furthermore we confirmed in our five BRAF-mutated human thyroid carcinoma cell lines that DUSP5 and DUSP6 induction was blocked by MEK inhibition, using a highly potent and selective MEK inhibitor namely AZD6244." (PMID 28910386, 2017). "The BRAF mutation has a very high specificity and positive predictive value for thyroid cancer." (PMID 26886957, 2016). "We investigated the role of PD-L1 in thyroid cancer with respect to BRAF mutation and MAP kinase pathway activity and the effect of anti PD-L1 antibody therapy on tumor regression and intra-tumoral immune response alone or in combination with BRAF inhibitor (BRAFi)." (PMID 26943572, 2016). "However, little is known about the impact of TERT promoter mutations and ALK rearrangement in thyroid cancer patients with a high prevalence of BRAF mutations." (PMID 26857243, 2016). "Moreover, biomarkers related to thyroid function and BRAF mutation testing were only obtained for the thyroid cancer patients." (PMID 26985827, 2016). "Multiple molecular abnormalities have been described in thyroid cancers arising from ovarian teratomas, including point mutations in BRAF (V600E and K601E) 67% of cases and KRAS and NRAS as well as loss of heterozigocity in the PTEN region and ret/PTC rearrangements." (PMID 27882257, 2016). "Recently, molecular diagnostics has offered new techniques for detecting the most common mutations in thyroid cancer (BRAF, RAS, RET/PTC, and PAX 8/PPAR γ) in order to optimize the management of indeterminate follicular lesions and to guide the therapeutic approach more appropriately." (PMID 26693224, 2015).
thyroid cancer (continued). "In transgenic mice, BRAFV600E induces the development of thyroid cancer with high penetrance and short latency, thus suggesting that BRAF mutations may function as the initial transforming event during thyroid tumor development." (PMID 26392334, 2015). "Two areas of potential interest are the findings that BRAF mutations may be useful in predicting papillary thyroid cancer aggressiveness and the use of microRNA expression patterns to predict thyroid cancer recurrence after surgery." (PMID 25192282, 2014). "Our data have demonstrated that combine analysis of BRAF mutation and DNA methylation markers on FNABs may be a useful strategy to facilitate the diagnosis of malignant thyroid neoplasm, particularly PTC." (PMID 24588959, 2014). "PLX4032 has potent anti-proliferative effects selectively in BRAF-mutated thyroid cancer cells." (PMID 24673746, 2014). "As a consequence, BRAF-mutated thyroid cancers are densely infiltrated with tumor-associated macrophages, which may account for up to 50% of the total mass of the tumor." (PMID 24982657, 2014). "In human thyroid cancer BCPAP cells harboring homozygous BRAF V600E mutation, BRAF V600E inhibitor, PLX4032, and MEK inhibitor, AZD6244, increased histone acetylation of the NIS promoter, suggesting that BRAF V600E normally maintained histone in a deacetylated state at the NIS promoter." (PMID 24243688, 2014). "Thyroid cancer, recognized as highly vascular, also has multiple associated somatic mutations of proto-oncogenes v-Raf murine sarcoma viral oncogene homolog B (BRAF), V-Ki-ras2 Kirsten rat sarcoma viral oncogene homolog (K-Ras), and rearranged during transfection (RET)." (PMID 26328220, 2014). "This specific V600E BRAF mutation represents 99% of all BRAF mutations found in thyroid cancer." (PMID 24987460, 2014). "BRAF mutations in thyroid cancers appear to be over reported (90% in this study vs. 40% in COSMIC)." (PMID 23991070, 2013). "The mutant BRAF inhibitors may also be useful for treating other cancers that are BRAF mutation positive, such as colon cancer, lung cancer, and thyroid cancer." (PMID 23755373, 2013). "Indeed, deregulated activation of the MAPK cascade via mutations and/or rearrangements in RET, RAS, and BRAF genes occurs in ~70% of papillary thyroid carcinomas (the most common subtype of thyroid cancers)." (PMID 22927847, 2012). "Our prior study suggests that MAP kinase activation due to BRAF gene mutation in thyroid cancer may contribute to increased MICA/B expression." (PMID 21605422, 2011). "The BRAF V600E mutation represents more than 90% of BRAF mutations found in thyroid cancer." (PMID 22654559, 2011). "Although the prevalence of BRAF mutations in thyroid cancer was much lower than the 51% previously published, this discrepancy could be explained by the presence of histologies other then papillary." (PMID 21829508, 2011). "Recently, it was investigated whether sensitivity to MEK inhibition was determined by oncogene status in 13 human thyroid cancer cell lines: four with BRAF mutations, four RAS, one RET/PTC1, and four wild type." (PMID 20628483, 2010). "Whether BRAF mutations uniquely predict response to MEK inhibitors in thyroid cancer will need further in vitro and in vivo study." (PMID 17179987, 2007). "In addition, RET/PTC is more prevalent in childhood thyroid cancers, whereas BRAF V600E mutations are extremely rare in children and the age of patients with PTCs who express BRAF V600E is more than that of the general PTC population." (PMID 17179987, 2007). "This indicates that BRAF mutations may contribute to poor prognosis in thyroid cancer patients." (PMID 40723292, 2025).
thyroid cancer (continued). "Future studies should also evaluate bavachinin’s effects in other thyroid cancer subtypes and investigate potential synergistic effects with existing kinase inhibitors or chemotherapy, especially in aggressive tumors harboring dual pathway activations (e.g., BRAF/PTC or RAS mutations)." (PMID 41477125, 2025). "Additionally, our focus on the BRAF V600E mutation, limited exploration of other prevalent molecular factors in thyroid cancer, and the observed discrepancies regarding HT and thyroid cancer risk highlight the need for more extensive molecular and mechanism research in this field." (PMID 39568807, 2024). "In our previous studies, we investigated the diagnostic potential of several types of molecular markers: BRAF V600E mutation, and the relative expression of miRNA and protein-coding genes, as well as the mitochondrial/nuclear DNA ratio for preoperative detection of thyroid cancer." (PMID 39000197, 2024). "Moreover, we made a brief review of rare BRAF mutations in thyroid carcinomas." (PMID 39288226, 2024). "The intra-tumoral immune cell density correlates with BRAF V600E mutation and low thyroid differentiation scores, while PD-L1 positivity has been shown to correlate with lymph node metastasis, extra-nodal invasion, tumor recurrence, and poor survival in thyroid cancer patients." (PMID 38255638, 2023). "However, TERTp mutation may be a second genetic event following oncogenic activation, such as IDH mutation in diffuse gliomas, BRAF V600E mutation in thyroid cancer, and FGFR3 mutation in urothelial carcinoma." (PMID 37185778, 2023). "However, 68.4% of PTC-BRAFwt also showed a high score of NOX4 protein, emphasizing that NOX4 expression could be upregulated in thyroid cancer independently of BRAF mutational status." (PMID 37504283, 2023). "In addition to selective RET inhibition for the treatment of patients with RET alterations, inhibitors of NTRK fusions (tropomyosin receptor kinase [TRK] inhibitors) and BRAF mutations (BRAF inhibitors) have either been approved or have shown promising activity in thyroid cancer." (PMID 37207147, 2023). "However, later studies clearly showed that in the context of untreated invasive human carcinomas from colon and BRAF-mutated thyroid cancer patients, significant numbers of senescent cells could be present in the primary tumor." (PMID 36980745, 2023). "Both serous BOTs and a subset of thyroid gland cancers are associated with BRAF mutations; thus, there is a possibility that women with serous BOTs who subsequently develop thyroid gland cancer may have BRAF mutations." (PMID 37807065, 2023). "In addition, BRAF mutations were associated with the sensitivity of thyroid cancer cell lines." (PMID 37297004, 2023). "A timely comprehensive molecular testing of those cases wild-type for the common thyroid carcinoma BRAF V600E-like and RAS-like driver mutations may uncover actionable gene rearrangements that can be targeted by highly selective inhibitors with great potential benefit for the patients." (PMID 36578928, 2022). "To explore whether NGS can increase the accuracy of diagnosis compared with methods based on the detection of BRAF mutations, we analyzed the diagnostic specificity and sensitivity of thyroid cancer by FNA cytology combined with ThyroLead or with ARMS-qPCR for BRAF mutation merely." (PMID 34322384, 2021). "Associations of osteopontin expression and mutated BRAF may represent another prospective source of evidence according to which osteopontin could be inducing EMT in thyroid cancer, whereby BRAF mutation, especially BRAF V600E, is closely related to EMT activation." (PMID 34680488, 2021). "Furthermore, a pre-clinical study recently showed that BRAF V600E + thyroid cancer cell lines displayed higher resistance to radiation, and forced expression of a BRAF V600E mutation into wild-type BRAF thyroid cancer cells resulted in increased radiation resistance in vitro." (PMID 34537078, 2021).
thyroid cancer (continued). "In this pilot study, we aim to prospectively screen for the BRAF (V600E) mutations in the plasma of patients undergoing surgery for thyroid nodules to assess the sensitivity and accuracy of ctDNA for the detection of thyroid cancer and to evaluate its value as a tool for thyroid cancer surveillance." (PMID 34475951, 2021). "A case report showed that nivolumab could benefit thyroid cancer with BRAF V600E gene mutation." (PMID 34266418, 2021). "Furthermore, BRAFV600E mutation represents 98–99% of all BRAF mutations in thyroid cancer." (PMID 34359735, 2021). "However, the origin of BRAF mutations in thyroid cancer still needs clarification." (PMID 27793009, 2017). "Thus, the BRAF V600E mutation is an independent risk factor that may be used to predict thyroid cancer persistence/recurrence." (PMID 24396464, 2014). "AsuragenmiR Inform (Austin, TX, USA) mutation analysis assay and Thyroid Cancer Mutation Panel by Quest Diagnostics (Madison, NJ, USA) are the two main commercially available mutational tests which test for known genetic alterations such as BRAF, RAS, RET/PTC, and PAX8/PPARγ." (PMID 24808946, 2014). "The demonstration that BRAF mutations are associated with silencing of iodine-transporting genes in thyroid cancer indicates that targeting BRAF may contribute for improving the iodine uptake ability of thyroid cancer cells." (PMID 22654560, 2011). "BRAF V600E mutations may be associated with thyroid cancer progression, have been defined as thyroid oncogenes experimentally, and may be, in part, responsible for tumour dedifferentiation and loss of response to standard therapies, such as TSH suppression and radioiodine." (PMID 17179987, 2007). "Recent findings revealed that BRAF mutations are usually rare in childhood thyroid carcinoma, both sporadic and radiation related, suggesting that thyroid carcinomas involving a BRAF mutation may have a longer latency period than those involving gene rearrangements." (PMID 15812549, 2005). "H&N cancers comprised 140 patients (3-4%), primarily secretory salivary carcinoma in NTRK trials (n = 12-20), thyroid carcinoma in BRAF (n = 36) and RET (n = 45) programs, and rare HER2-positive salivary duct carcinomas." (PMID 41827789, 2026). "This study demonstrated that dabrafenib plus trametinib is effective in Japanese patients with BRAF V600E-positive thyroid cancer, with ORRs of 50% for PTC and 67% for ATC." (PMID 40844731, 2025). "By combining molecular and imaging data, BRAF V600E testing plays a pivotal role in advancing thyroid cancer diagnosis and treatment." (PMID 40970023, 2025). "Studies have investigated the effects of BRAF inhibitors such as vemurafenib and dabrafenib on cell growth and redifferentiation strategies in BRAFV600E mutated thyroid cancer cell lines." (PMID 40129883, 2025). "In resistant thyroid cancer cells treated with a BRAF inhibitor, fibronectin levels increased, promoting invasiveness and potential metastasis." (PMID 40129883, 2025). "In this review, we analyze BRAF V600E as both a prognostic marker and a therapeutic target in thyroid cancer." (PMID 41368991, 2025). "Our findings unveil TAZ as an actionable therapeutic target to overcome resistance to BRAF inhibitors in undifferentiated thyroid cancer." (PMID 40667288, 2025). "ATC, representing <1% of thyroid cancers, is reclassified in the fifth WHO edition alongside squamous cell carcinoma, a newly defined subtype sharing follicular cell origin, frequent BRAF mutations, and similarly poor outcomes." (PMID 41164799, 2025). "For example, in BRAF (V600E)–mutant thyroid cancer cells, treatment with the BRAF inhibitor PLX4032 was partially ineffective because of overexpression of c-Met, which in turn activated the PI3K/Akt and MAPK pathways." (PMID 40125551, 2025).
thyroid cancer (continued). "Recent research has highlighted the role of fibronectin in the treatment of BRAF-mutant thyroid cancer." (PMID 40129883, 2025). "Our rationale for employing a broad gene panel stems from emerging evidence that thyroid cancer pathogenesis involves complex genomic landscapes beyond canonical drivers like BRAF and RAS." (PMID 40805132, 2025). "BRAF-mutant thyroid cancer cells are known to rely heavily on glycolysis compared to their wild-type counterparts." (PMID 40063000, 2025). "The development of dabrafenib as a targeted therapy for thyroid cancer has transformed the treatment landscape for BRAF-mutant thyroid malignancies, particularly ATC and RAI-refractory DTC." (PMID 41368991, 2025). "The accumulation of further data is required to establish the appropriateness of prioritizing tumor-agnostic therapies for BRAF V600E-positive thyroid cancer." (PMID 40844731, 2025). "In summary, the clinical development of dabrafenib, particularly in combination with trametinib, has significantly reshaped the therapeutic landscape for BRAF-mutant thyroid cancers." (PMID 41368991, 2025). "While BRAF and RAS mutations are more common in thyroid cancer, the identification of this rare MET fusion contributes to the limited but growing body of literature on kinase fusion-driven thyroid carcinomas." (PMID 40636652, 2025). "ROS can initiate inflammatory responses, cause DNA damage, and lead to oncogenic mutations such as those in BRAF and RAS genes, thereby increasing the aggressiveness and progression of thyroid cancer." (PMID 40723913, 2025). "This study assessed the effect of DSF/Cu on thyroid cancer cells and the response of these cells to the BRAF kinase inhibitor PLX4032." (PMID 39940256, 2025). "Studies have shown that various agents, including retinoids (vitamin A-derived retinoic acids), the MEK inhibitor selumetinib, and BRAF inhibitors such as vemurafenib and dabrafenib, can induce redifferentiation in thyroid cancer cells." (PMID 39499416, 2025). "Collectively, our findings unveil TAZ as a new target to overcome resistance to BRAF inhibitors in undifferentiated thyroid cancer." (PMID 40667288, 2025). "As with selumetinib, a second therapeutic strategy sought to enhance RAI uptake in refractory thyroid cancers by leveraging vemurafenib-induced redifferentiation seen in genetically engineered mouse models with conditional BRAF V600E activation." (PMID 41368991, 2025). "Similar findings have been reported in other single-institution cohorts, where BRAF testing demonstrated high specificity but lower sensitivity for thyroid cancer detection." (PMID 41303583, 2025). "The activation of the MAPK pathway via T1799A point mutation in the BRAF gene, which gives rise to the BRAFV600E protein, appeared to be relatively infrequent in radio-induced thyroid cancers." (PMID 40362680, 2025). "Next, we addressed the role of FAK degradation in the BRAF-mutant thyroid cancer cells, BCPAP and 8505C." (PMID 40458728, 2025). "Given the relatively poor response of selumetinib in BRAF-mutant thyroid cancer, other MAPK inhibitors have been explored for redifferentiation strategies." (PMID 39499416, 2025). "BRAF inhibitors induce feedback activation of the RAS pathway in thyroid cancer cells, potentially leading to drug resistance." (PMID 40129883, 2025). "He helped in the treatment of H-RAS-driven tumors with FTIs and in targeting the adaptive responses of BRAF or RAS-mutant thyroid cancers to RAF/MEK inhibitors with bispecific antibodies to TSHR and/or HER2." (PMID 39874138, 2025). "This review explores the role of BRAF V600E in thyroid cancer with emphasis on its debated prognostic value, notable molecular heterogeneity, and opportunities as a therapeutic target." (PMID 41368991, 2025).